LYNX1-SLURP2 (LYNX1-SLURP2 readthrough)
Gene: Protein-coding gene on chromosome 8 (142,764,334 to 142,778,224, reverse strand). Ensembl gene ENSG00000284505.
Genetic constraint (gnomAD): Loss-of-function variants: 9 observed, 12.46 expected, observed/expected ratio (o/e) 0.72, 90% interval 0.43 to 1.26. The upper end of that interval is the gene's LOEUF score, 1.26, which puts it in group 5 of 6, group 1 being the genes least tolerant of losing a copy. Missense variants: 170 observed, 177.55 expected, observed/expected ratio (o/e) 0.96, 90% interval 0.84 to 1.09. Synonymous variants: 65 observed, 68.89 expected, observed/expected ratio (o/e) 0.94, 90% interval 0.77 to 1.16.